PROS1 (protein S)
Diseases named in the same sentence as PROS1 in open-access papers (continued):
Sharing a sentence is not in itself a finding about the gene and the disease.
tumor (continued). "The expression levels of PROS1 (P = .001), CLU (P < .001), and LRG1 (P = .002) were significantly lower in PTC patients with large tumor size (>2 cm) than in small tumor size patients (≤2 cm), respectively." (PMID 40797389, 2025). "Single‐cell data indicate that PROS1, a key TAM signal, is specifically expressed in tumor epithelial cells, CAFs, and endothelial cells from progressive tumors, while its expression is minimal in normal thyroid tissues." (PMID 40433916, 2025). "Mechanistically, PROS1 modulated the peripheral inflammation and immune responses, rather than the TAM-related signals within tumor cells, which ultimately decreased tumor metastasis." (PMID 40756366, 2025). "Meanwhile, CAFs are found to secrete PROS1 and GAS6, which can activate AXL receptors on the surface of tumor epithelium cells, promoting immune suppression and tumor progression in ACPs." (PMID 40299526, 2025). "Inverse correlations were found between the IHC scores of PROS1 (P = .024), CLU (P = .010), and LRG1 (P = .038) and PTC patients with higher tumor classification, respectively." (PMID 40797389, 2025). "The PROS1–MERTK interaction plays a role in cancer progression, promoting immune evasion and metastasis in multiple cancers by fostering a tumor-supportive microenvironment." (PMID 39535659, 2025). "For example, the PROS1-AXL pathway mediates the interaction between MICA+ tumor cells and MMP9+ macrophages, to facilitate tumor immune escape in advanced HCC." (PMID 39981249, 2025). "These insights deepen our understanding of the PROS1–MERTK interaction role in immune modulation and tumor progression, unveiling potential targets for cancer immunotherapy." (PMID 39535659, 2025). "The spatial expression and distribution of PROS1 and MERTK on H&E pathological sections aligned with single‐cell analysis, showing their primary distribution in tumor areas and increased expression as PTC progressed." (PMID 40433916, 2025). "Consistent with our previous research, we observed a significant upregulation of PROS1 in MICA+ and IRF1+ tumor cells." (PMID 38254761, 2024). "Through this analysis, we elucidated the interactions between MICA+ tumor cells and MMP9+ macrophages, primarily mediated via the PROS1-AXL axis in advanced HCC." (PMID 38254761, 2024). "The interaction between MICA+ tumor cells and MMP9+ macrophages was mediated through the PROS1-AXL pathway." (PMID 38254761, 2024). "We employed scRNA-seq analyses to investigate the communication between MICA+ tumor cells and MMP9+ macrophages via the PROS1-AXL axis and revealed an upregulation of the IFN-γ signaling pathway in MICA+ tumor cells." (PMID 38254761, 2024). "Subsequently, experiments validated that DNA damage not only induced MICA expression in tumor cells via IRF1, but also upregulated PROS1 levels in HCC cells, stimulating macrophages to secrete MMP9." (PMID 38254761, 2024). "Initially, we assessed the mRNA and protein expression levels of PROS1 and AXL across various human tumor types using the Human Protein Atlas (HPA) database." (PMID 38254761, 2024). "We identified the existence of an interaction between MICA+ tumor cells and MMP9+ macrophages mediated via the PROS1-AXL axis." (PMID 38254761, 2024). "Ligand–receptor pairs, such as PROS1-AXL, NAMPT-INSR, MDK-LRP1, MDK-ALK, GAS6-MERTK, and GAS6-AXL, between endothelial and tumor cells exhibited a higher communication possibility than that between endothelial cells and thyrocytes." (PMID 37733241, 2023). "TAM receptors and their ligands PROS1 and GAS6 are frequently overexpressed in cancer and mediate tumor-stroma interaction to limit anti-tumor immunity and fuel cancer growth." (PMID 36509738, 2022). "PtdSer has also attracted considerable attention in recent years as a crucial costimulatory factor for the TAM pathway, directly participating in PROS1-AXL-mediated innate immunity and tumour microenvironment regulation." (PMID 36203174, 2022).
tumor (continued). "Our results demonstrated that PROS1 expression was significantly positively correlated with the presence of most immune cells in LGG tissue, the expression of biomarkers by tumour-infiltrating immune cells, and the expression of immune checkpoint genes." (PMID 35879775, 2022). "Therefore, the study showed that the increased PROS1 may promote tumor immune escape." (PMID 36685506, 2022). "Inhibiting Pros1 and TLR7, 8 is beneficial to promote the polarization of TAM toward M1 and is beneficial to anti-tumor responses." (PMID 33391402, 2021). "It has been shown that Protein S activation of either MerTK or Tyro3 inhibits LPS and IFN-γ induced M1 polarization of peritoneal and tumor-derived mouse macrophages, indicated by decreased expression of M1 marker genes Il1, Il6, Cd86 and Tnf." (PMID 31088471, 2019). "In conclusion, our data indicate PROS1 is a potential therapeutic target in OSCC, preventing tumor cell proliferation and migration." (PMID 28118606, 2017). "Tumors inhibited for PROS1 expression were characterized by attenuated proliferation coupled with increased apoptotic foci, in agreement with AXL being a mediator of tumor cell survival." (PMID 28118606, 2017). "In summary the role of Gas6/protein S and the TAM receptors remains controversial in solid tumors with different roles depending on the tumor entities." (PMID 27486820, 2016). "For instance, targeting the salt bridges at the binding interface might be a potential approach to inhibit the PROS1-MERTK interaction, thereby alleviating immunosuppression and enhancing anti-tumor immune responses." (PMID 39535659, 2025). "Notably, we observed the presence of L-R interactions involving PROS1-AXL and CCL15-CCR1 between MICA+ tumor cells and MMP9+ macrophages." (PMID 38254761, 2024). "However, recent studies have provided evidence that PROS1 can also activate AXL in tumor cells, thereby promoting tumor cell proliferation and invasiveness." (PMID 38254761, 2024). "Furthermore, the TAM signaling pathway is widely active in various body tissues, including in tumour cells that upregulate TAM signaling through autocrine and paracrine PROS1 or GAS6, thereby facilitating a more favourable environment for tumour growth." (PMID 36203174, 2022). "Similarly, GAS6 and PROS1 were significantly increased, and there was a trend toward increased MERTK expression in tumor biopsies from patients with EGFRMT NSCLC after treatment with OSI." (PMID 35708914, 2022). "Activation by phosphatidyl serine (PtdSer) externalized on apoptotic cells complexed with the protein ligands protein S1 (PROS1) or growth arrest specific factor 6 (GAS6) leads to activation of downstream pathways, including PI3K/AKT and MAPK/ERK, and promotes tumor cell survival." (PMID 35708914, 2022). "PROS1 expression was significantly correlated to lymph nodes classification (P = 0.02) but not statistically correlated with patients’ age, gender, tumor classification, extrathyroidal invasion, and BRAFV600E mutation." (PMID 34414029, 2021). "In our study, we show that PROS1 mRNA is significantly decreased in cancer tissues and peripheral plasma of ICC patients, which might play a role as a tumor suppressor gene in ICC." (PMID 31956102, 2020). "Secretion of PROS1 by melanoma cells was shown to skew host macrophages towards the anti-inflammatory M2-like phenotype, in a MERTK and TYRO3-dependent manner, allowing a tumor-permissive environment." (PMID 31775787, 2019). "Tumor cells differ in their expression profile of TAM RTKs and PROS1." (PMID 28675785, 2017). "In cancer settings, the activation of TAM receptors by GAS6 was shown in several tumor models, however the role of PROS1 in oncogenic signaling and tumor biology has not been extensively investigated." (PMID 28118606, 2017).
tumor (continued). "This stems from the fact that Vit-K-dependent γ-carboxylation of Gas6/Pros1 is widely, if not ubiquitously, expressed in non-hepatic cells that include many of the cells that express Gas6 in the tumor microenvironment." (PMID 27916840, 2016). "PROS1‐AXL communication was tumor‐specific and absent in normal tissues." (PMID 40433916, 2025). "Additionally, PTC patients with tumor extrathyroidal extension had significantly lower PROS1, CLU, and LRG1 IHC scores compared to patients without extrathyroidal extension (P = .001, P = .001, and P = .001, respectively)." (PMID 40797389, 2025). "Additionally, the significant association between immune checkpoint genes and PROS1 indicated that targeting PROS1 might increase the efficacy of immunotherapy in LGG, which was consistent with the Tumor Immune Dysfunction and Exclusion (TIDE) results." (PMID 35879775, 2022). "Classically, their ligands protein S (PROS1) and growth arrest specific 6 (GAS6) are secreted by macrophages and cancer cells to activate PI3K, extracellular signal-regulated kinase (ERK), and NFκB pathways to promoted tumor proliferation and immune suppression." (PMID 31396227, 2019). "It was recently reported that FMRP does not impact tumor cell growth but facilitates immune evasion by controlling CCL7, IL-33, and PROS1." (PMID 41513619, 2026). "PROS1 and GAS6 are produced by tumor cells and nonneoplastic cells in TME, which function as bridging molecules that are the physical link between MerTK and Phosphatidylserine (PtdSer)." (PMID 36497444, 2022). "Besides, we further found that PROS1 expression in 166 tumor tissues was higher than in 1157 normal samples in GBM (P < 0.001), and expression of PROS1 in 523 tumor tissues were higher than that in 1152 normal samples in LGG (P <0.001)." (PMID 36685506, 2022). "The lncRNA RP11-328K4.1, miRNA hsa-miR-27a-3p and mRNA PROS1, which are central nodes with high connectivity in the ICC ceRNET, exhibited great ability to distinguish ICC tumor tissues and matched adjacent nontumor tissues and to distinguish ICC tumor stages." (PMID 31956102, 2020).
cancer (403 papers, 1963 to 2026). A tumor composed of atypical neoplastic, often pleomorphic cells that invade other tissues. "Upregulation of PROS1 has also been associated with increased metastatic risk in other cancer types." (PMID 35954340, 2022). "We analysed the association of PROS1 expression with genomic heterogeneity and cancer stemness in patients with LGG." (PMID 35879775, 2022). "The TAM (Tyro3, Axl, MerTK) subfamily of receptor tyrosine kinases (RTKs) and their ligands, Gas6 and protein S (ProS1), are implicated in tumorigenesis and chemoresistance in various cancers." (PMID 32664510, 2020). "It had been reported previously that MerTK- or PROS1-deficient mice display lower levels of IL-10 production by myeloid cells following bacterial or viral activation, or in cancer models." (PMID 33101282, 2020). "In conclusion, we have shown that ProS1 is the most prominent functional ligand for Tyro3 RTK in human cancer cells and that it is linked to the Erk signalling pathway, distinct from the more well-characterised Gas6-Axl-Akt signalling axis." (PMID 31766614, 2019). "This indicated interruption of underlying cancer-mediated thrombosis and repletion of PC and protein S." (PMID 27264137, 2016). "Usually cancer patients are prone to develop thrombosis either as paraneoplastic phenomena or due to hypercoagulable state caused by reduced protein C, protein S, antithrombin III and increased cytokines." (PMID 27543099, 2016). "In addition to the protein S Tokushima mutation, the patient harbored thrombotic risk factors due to his history of cancer and smoking." (PMID 41567132, 2026). "It is necessary to conduct additional in vitro and in vivo testing to confirm whether there are distinct molecular mechanisms underlying PROS1’s functions in various cancers." (PMID 40797389, 2025). "The association between PROS1 and malignant tumors has also been defined by some researchers." (PMID 34414029, 2021). "Our most important finding is a possible involvement of Notch-2 and its signalling pathway (dynamin-2, nicastrin, SPARC and PROS1) in dormancy of cancer spheroids in a HMW-HA concentration (5 wt%) representative of normal brain ECM." (PMID 40881990, 2025). "Protein S-palmitoylation is integral to cancer growth and antitumor immunity, rendering it a compelling target for cancer treatment." (PMID 40066091, 2025). "The PROS pathway exhibited prominent Pros1-Axl interactions, most significant between cancer_macro 1/2 and cancer_macro 1 cells." (PMID 40723284, 2025). "Previous research has highlighted the critical roles of PROS1‐MERTK ligand‐receptor interactions in the development of various cancers." (PMID 40433916, 2025). "Meanwhile, they also demonstrated high expression of Pros1, which inhibits the polarization of M1‐like macrophages, and an exosome‐associated gene Cd63 in WT versus FMRP‐KO cancer cells analyzed by RNA‐seq and scRNA‐seq." (PMID 36968189, 2023). "Based on the improved understanding of the functions of novel human immune checkpoint inhibitors, 60 immune checkpoint genes (24 inhibitory, 36 stimulatory) were explored regarding their correlations with PROS1 in different cancer types." (PMID 35879775, 2022). "First, the pan-cancer analyses results showed that the expression of PROS1 was increased in different kinds of tumors, including GBM and LGG (P <0.001)." (PMID 36685506, 2022). "•The first LG domain (LG1) of protein S is essential for activation of Tyro3 and downstream signalling in human cancer cells." (PMID 35518197, 2022). "We have shown that ProS1 is a preferred ligand for Tyro3 over Gas6 in human cancer cells expressing both Tyro3 and Axl receptors, as well as identified Tyro3 signaling pathways that progress the cell cycle and support survival in cancer cells." (PMID 35518197, 2022). "Along with wildtype ProS1, these variants were added to both SCC-25 and MGH-U3 cancer cell lines which served as readouts for Tyro3 and Tyro3-dependent Erk kinase activation." (PMID 35518197, 2022).
cancer (continued). "Tumor-secreted protein S (ProS1) activates a Tyro3-Erk signaling axis and protects cancer cells from apoptosis, and thus supports cancer cell survival." (PMID 33947134, 2021). "As cancer cells also express the MERTK ligand Protein S (PROS1) and phosphatidylserine, this auto stimulatory loop leads to increased oncogenesis." (PMID 34835225, 2021). "Once saturating doses of PROS1 were reached—enough for both the T cells and the cancer cells—this effect was reversed as ligand competition was abrogated." (PMID 31664482, 2020). "The same profile of Tyro3 activation by ProS1 was also observed in several of the other cancer cell lines expressing Tyro3." (PMID 31766614, 2019). "As the roles of both Tyro3 RTK and ProS1 in cancer cell biology remained to be characterised, the Tyro3-activating abilities of both TAM ligands were compared." (PMID 31766614, 2019). "In this study, we have identified the ProS1-Tyro3-Erk axis as a signal transduction pathway in human cancer cells distinct from the previously reported Gas6-Axl-Akt axis." (PMID 31766614, 2019). "Our data show that ProS1 is an active and functional ligand for Tyro3 in human cancer cells, rapidly stimulating its phosphorylation as well as Erk, moreover, predominating over Gas6 as a ligand for this specific RTK." (PMID 31766614, 2019). "These novel data shed further light on the currently poorly understood roles of both Tyro3 and ProS1 in tumorigenesis and highlight Tyro3 as a novel cancer therapeutic target in addition to Axl." (PMID 31766614, 2019). "We also observed the same protective effects of ProS1 and Gas6 on viability of both cancer cells lines using an alternative apoptosis-inducing agent, cisplatin." (PMID 31766614, 2019). "Having shown that exogenous recombinant ProS1 activates Tyro3 and downstream Erk signalling in human cancer cells, we also investigated the effect of endogenous ProS1 secreted by human cancer cells as a functional Tyro3 ligand." (PMID 31766614, 2019). "Our results showed that ProS1 naturally secreted from cancer cells is functional in being able to activate Tyro3 and Erk kinase downstream to the same extent as recombinant ProS1." (PMID 31766614, 2019). "Here, we have focused on the specific role of Tyro3 expression and activation in cancers and attempted to delineate the downstream signalling pathways activated by ProS1-Tyro3 as compared to Gas6-Axl." (PMID 31766614, 2019). "Here, we show for the first time that PROS1 is highly expressed in OSCC cell lines SCC1 and SCC25, and provide evidence that PROS1 supports cancer cell proliferation and migration." (PMID 28118606, 2017). "Whereas the role of protein S in the coagulation system is well known, hardly anything is known about its function as a ligand for the TAM receptors in cancer, while some studies indicate an (over) expression of protein S in different cancers." (PMID 27486820, 2016). "In conjunction with active PROS1 signaling, C2 might contribute to cancer-related pain, a major determinant of patients’ quality of life." (PMID 41383633, 2025). "Understanding the functional implications of these salt bridges may provide valuable insights into the molecular mechanisms by which PROS1-MERTK interactions contribute to cancer progression." (PMID 39535659, 2025). "Collectively, our study suggests that PROS1 could serve as a biomarker for cancer diagnosis, prognosis, therapy selection, and follow-up." (PMID 35879775, 2022). "long non-coding RNA RP3-525N10.2-NFKB1-PROS1 triplet-mediated PROS1 expression could serve as a biomarker for cancer diagnosis, prognosis, therapy selection, and follow-up in LGG patients." (PMID 35879775, 2022). "The results indicated that high PROS1 expression was related to poor survival in several cancers (LGG, BCLA, STES, STAD, and UVM), and the pan-cancer analysis demonstrated similar results for disease-specific survival, disease-free interval, and progression-free interval." (PMID 35879775, 2022).